GZMB (granzyme B)
Diseases named in the same sentence as GZMB in open-access papers (continued):
Sharing a sentence is not in itself a finding about the gene and the disease.
acute myocardial infarction (5 papers, 2020 to 2025). Necrosis of the myocardium, as a result of interruption of the blood supply to the area. "There are several studies in which high levels of extracellular granzyme B have been associated with cardiac injury, including acute myocardial infarction, aortic aneurysm, or transplant vasculopathy." (PMID 35743021, 2022). "Finally, we reveal that elevated circulating levels of GRANZYME B in patients with acute myocardial infarction predict increased risk of death at 1-year follow-up." (PMID 33674611, 2021). "Here, we show that following acute myocardial infarction in mice, CD8+ T lymphocytes are recruited and activated in the ischemic heart tissue and release Granzyme B, leading to cardiomyocyte apoptosis, adverse ventricular remodeling and deterioration of myocardial function." (PMID 33674611, 2021).
celiac disease (5 papers, 2021 to 2024). An autoimmune genetic disorder with an unknown pattern of inheritance that primarily affects the digestive tract. "In celiac disease, decreased expression of protease inhibitor 9, a GZMB inhibitor, is a potential mechanism of enterocyte destruction and villous atrophy." (PMID 36011206, 2022). "GZMB was observed in mononuclear inflammatory cells present in the lamina propria, and EED samples exhibited a higher number of granzyme-positive cells when compared with both celiac disease cases and controls." (PMID 33524399, 2021).
Crohn disease (5 papers, 2017 to 2024). A gastrointestinal disorder characterized by chronic inflammation involving all layers of the intestinal wall, noncaseating granulomas affecting the intestinal wall and regional lymph nodes, and transmural fibrosis. "KLRG1+ CD8+ Trm cells are mostly found in the periphery and have a higher cytotoxic potential evidenced by the intracellular levels of granzyme B. In accordance, KLRG1+ CD8+ Trm cells were increased in inflamed tissue of Crohn’s disease patients compared to non-inflamed and controls." (PMID 34707610, 2021).
head and neck cancer (5 papers, 2018 to 2025). A primary or metastatic malignant neoplasm affecting the head and neck. "This could be particularly important in head and neck cancers, where GZMB expression has been associated both with favorable prognosis and with potential involvement in immunosuppressive mechanisms." (PMID 40766321, 2025). "The collected studies clearly demonstrate the importance of granzyme B in the diagnosis and prediction of treatment outcomes of patients with head and neck cancer." (PMID 40766321, 2025). "It has been shown that the protein responsible for granzyme B inactivation is Serpin B9, and data indicate that this protein is present in 4% of head and neck cancers." (PMID 40766321, 2025). "The blockade of Wee1 kinase also enhances natural-killer-cell-mediated granzyme-B-dependent cell lysis in head and neck cancer." (PMID 37296592, 2023). "Tumor cell resistance to granzyme B-induced cell death can be reversed through inhibition of WEE1 kinase as AZD1775 sensitized both murine and human head and neck cancer cells to NK lysis." (PMID 29925431, 2018). "Granzyme B (GZMB) and melittin are molecules with unique and distinct mechanisms of action that, in the context of head and neck cancers (HNSC), may serve as potentially complementary therapeutic tools." (PMID 40766321, 2025). "Studies performed on head and neck cancer biopsies utilizing the spatial architecture of the tumor have identified markers such as PD-L1, PD-1, STING, IDO1, GZMB, and Ki67 to be differentially expressed between different locations of the tumor and being predictive of progressive disease." (PMID 38044986, 2023).
inflammatory skin disease (5 papers, 2021 to 2024). Inflammatory skin disorders covers a broad category that includes many conditions ranging in severity, from mild itching to grave medical health complications These disorders are common in people of all ages and races. "GZMB was also proved important in the pathogenesis of inflammatory skin diseases due to GZMB-mediated proteolysis involved in processes such as tissue remodeling and autoantigen generations." (PMID 35958546, 2022). "IFN-γ and GzmB are key effector cytokines released by cytotoxic T cells that play a role in various inflammatory skin disorders." (PMID 35755042, 2022). "The most obvious significance of PRGs expression was observed in Granzyme B (GZMB), which was dramatically elevated in inflammatory skin disorders; it is known for its pro-apoptotic function, as well as epithelial barrier disruption." (PMID 36110207, 2022).
liver fibrosis (5 papers, 2019 to 2025). "Our previous study also showed that GZMB + T cells are increased in schistosome-associated liver fibrosis." (PMID 37817226, 2023). "MF2 cells specifically expressed liver fibrosis-related genes AGTR1, CYGB, PIEZO2, and LPL, and MF5 cells specifically highly expressed immune-related genes TRAC, CD3D, GZMB, and FCGR3A." (PMID 40949143, 2025). "On the other hand, granzyme B expression by lobular Kupffer cells and CD11b+ cells correlated negatively with histological inflammation, whereas granzyme B expression in portal (but not lobular) T and B cells correlated positively with hepatic fibrosis and/or periportal inflammation." (PMID 33621209, 2021). "Increased numbers of IFN-γ+ naïve cells may seem like a curious finding yet has been previously reported along with increased granzyme B expression yet was not stratified by the degree of liver fibrosis." (PMID 31456810, 2019).
pneumonia (5 papers, 2021 to 2025). An acute, acute and chronic, or chronic inflammation focally or diffusely affecting the lung parenchyma, caused by an infection in one or both of the lungs (by bacteria, viruses, fungi, or mycoplasma.). "In addition, molecular signatures of cell-mediated immunity, such as IL12p40, IFNG, and GZMB, in the M5 group were specifically and significantly higher than those in the NC, M4, and severe groups, suggesting their protective and pathogenic roles in moderate pneumonia." (PMID 36776879, 2023). "The expression levels of CD40L, Eomes and Granzyme B were significantly higher in patients with acute pneumonia, which indicates that the differentiation promotion of CD4+ T cells into Th17 and IgE secretion might be inhibited." (PMID 34841705, 2021). "Nevertheless, several of them, SELL, GZMB, and CCR7 (at 3 dpi), and HAVCR2 (TIM-3), TNFRSF9 (CD137), and GPR18 (at 6 dpi) were promptly upregulated for the virulent Lena strain, probably associated with the marked clinical signs, the earlier and stronger peak of replication, and severe pneumonia." (PMID 34851149, 2022). "The frequency of cluster 9 was identified as DNT cell with markers of CD3+ TCRd+CD45RA+CCR7−CD11c+CD45RO+ T‐box expression in T‐cell (Tbet)+ Granzyme B+, and was one of the increased subsets of CD3+ T cells in acute pneumonia." (PMID 34841705, 2021).
pulmonary tuberculosis (5 papers, 2020 to 2023). A bacterial infection that affects the lungs and is caused by Mycobacterium tuberculosis. "But, the expression of granzyme A, granzyme B, and perforin in patients with active pulmonary tuberculosis was higher than those in the healthy controls and patients with latent M. tuberculosis infection, and it decreased after curing." (PMID 37761328, 2023). "Previous investigations have demonstrated that 1,25(OH)2D3 downregulates the cytotoxic effector response in pulmonary tuberculosis by reducing the expression of perforin, granulysin, and granzyme B." (PMID 35563767, 2022). "Analysis indicated that granzyme B was increased significantly in pulmonary TB patients with cavity." (PMID 34646890, 2021). "Increased abundance of granzyme A and granzyme B was observed in culture supernatants of NK cells isolated from pulmonary TB patients with cavity and cocultured with MTB protein lysates." (PMID 34646890, 2021). "However, the intracellular granzyme-B expression by specific lymphocyte populations and the elevated serum levels in patients with active pulmonary TB indicate the host defense against Mtb." (PMID 32823923, 2020). "In TB patients, a slightly increased expression of granzyme-B was shown in CD8+ and CD4+ T cells, but not NK cells, which is contradict to the recent findings that active pulmonary TB patients downregulated granzyme-B expression in CD8+ T cells in comparison with latent TB infection." (PMID 32823923, 2020).
allergic asthma (4 papers, 2014 to 2024). A asthma with a basis in a pathological type I hypersensitivity reaction. "During acute exacerbation of allergic asthma in children, gram‐negative microbes were increased prominently, showing a relationship with increased granzyme B, MIP‐1β, and PD‐L1 in induced sputum." (PMID 34667591, 2021).
breast invasive carcinoma (4 papers, 2020 to 2022). "One interesting finding was that some cancers showed a large amount of FoxP3 expression with minor GzmB expression such as lower grade glioma (LGG), invasive breast carcinoma (BRCA) and ovarian serous cystadenocarcinoma (OV)." (PMID 35326588, 2022). "In the Finak dataset, the expression of GZMB was 4.910 times higher in invasive breast carcinoma than normal tissue." (PMID 33042828, 2020).
cerebral malaria (4 papers, 2014 to 2019). A sequestration of Plasmodium falciparum in the brain, which can cause coma and/or seizures. "However, granzyme B has also been implicated in the development of cerebral malaria and the increased granzyme B levels could also reflect degranulated and exhausted CD8+ T-cells, further illustrating the dual effects of the immune response during malaria infection." (PMID 30563486, 2018). "In experimental cerebral malaria, granzyme B has been defined as a critical factor in promoting fatal cerebral pathology." (PMID 25337791, 2014). "CD8+ T cells are known to play an important role in experimental cerebral malaria (ECM) by migrating to the brains and by exerting cytotoxic activities through granzyme B and perforin." (PMID 29034214, 2017).
Chagas disease (4 papers, 2015 to 2022). A parasitic infection caused by Trypanosoma cruzi. "Cytotoxic CD4+ T cells co-expressing granzyme B and perforin were expanded in patients with Chagas disease and were higher in patients with mild CCC compared to controls." (PMID 36447264, 2022). "A cytotoxic profile that co-expresses both molecules (perforin and granzyme B) combined with cytokine production has been described for CD8+ T cells in patients with a mild form of Chagas disease." (PMID 29750791, 2018). "Cytokine-secretion and Granzyme B response to TcCA-2 epitopes by PBMCs from HLA-A*02:01 Chagas disease patients and healthy donors." (PMID 25816096, 2015). "The TcCA-2-specific CD8+ T cells were functionality evaluated by Granzyme B and cytokine production in peripheral blood mononuclear cells (PBMC) from Chagas disease patients stimulated with the identified HLA-A*02:01 peptides." (PMID 25816096, 2015). "Furthermore, we found an increased proportion of CD4+granzyme-perforin+ T cells in CCC versus IND Chagas disease patients and that CCC had a CD4+granzyme B+INF-γ+ T cell population, which was absent in IND." (PMID 33539379, 2021).
chronic hepatitis B (4 papers, 2017 to 2023). "Granzyme-B+ Trm were found to be enriched during CXCR3+ chronic hepatitis B infection, antagonizing tolerance and adding to liver damage." (PMID 37056783, 2023). "A high dose of Ad-HBV-Luc developed into chronic hepatitis B accompanied by dysfunctional CD8 T cells characterized by high expression of PD1 and TOX and low expression of KLRG1 and GzmB." (PMID 34835079, 2021).
diffuse large B-cell lymphoma (4 papers, 2018 to 2024). "In another study, 17 diffuse large B-cell lymphoma (DLBCL) patients also received MGD013, and serum IFN-γ was significantly increased > 140-fold above baseline, as well as associated lytic markers (i.e., perforin and granzyme B)." (PMID 38581716, 2024).
graft versus host disease (4 papers, 2016 to 2025). An immune system disorder that occurs after allogeneic hematopoietic stem cell transplant and is a reaction of donor immune cells against host tissues. "Previous studies using allogeneic hematopoietic cell transplantation (allo-HCT) murine models showed that GzmB is required for CD8+ T cells to cause graft-versus-host disease (GVHD)." (PMID 27774524, 2016). "Several studies suggest that GzmB plays differential roles in graft-versus-host disease (GVHD) and graft-versus-tumor effect mediated by different types of donor T cells." (PMID 38846935, 2024). "For example, in models of graft-versus-host disease and graft-versus-leukemia, GzmB is absent in dLNs but present in the skin." (PMID 38833303, 2024).
head and neck squamous cell carcinoma (4 papers, 2021 to 2025). A squamous cell carcinoma that arises from any of the following anatomic sites: lip and oral cavity, nasal cavity, paranasal sinuses, pharynx, larynx, and salivary glands. "Analyses of available data, covering a broad spectrum of tumor, show that GZMB expression in head and neck squamous cell carcinoma (HNSC) is increased, compared to normal tissues." (PMID 40766321, 2025). "Granzyme B (GZMB) and melittin are potent cytotoxic agents with promising applications in cancer immunotherapy, particularly in head and neck squamous cell carcinoma (HNSC)." (PMID 40766321, 2025).
hemophagocytic lymphohistiocytosis (4 papers, 2008 to 2024). "Up-regulation of miR-30e diminished NK cell cytotoxicity in patients with hemophagocytic lymphohistiocytosis (HLH) by targeting granzyme B and perforin." (PMID 38339220, 2024).
Hodgkins lymphoma (4 papers, 2009 to 2024). A heterogeneous group of malignant lymphoid neoplasms of B-cell origin characterized histologically by the presence of Hodgkin and Reed-Sternberg (HRS) cells in the vast majority of cases. "One cHL with nodular sclerosis subtype is described to be of rare T-cell differentiation, identified by missing expression of the transcription factor PAX-5 and positive staining for granzyme B in the H-RS cells." (PMID 39001514, 2024).
kidney cancer (4 papers, 2019 to 2025). Primary or metastatic malignant neoplasm involving the kidney. "Interestingly, our analysis found that GZMB is a positively correlated gene in kidney cancer." (PMID 34906145, 2021).
latent infection (4 papers, 2015 to 2025). "In contrast to EBNA-2 PRS-specific CD4+ T-cells during latent infection, perforin and granzyme B expression by NIL-specific CD4+ T-cells was in the absence of continued activation as shown by their lack of CD38 expression." (PMID 34882759, 2021). "The term-Tem subcluster, characterized by increased gene expression of multiple cytotoxic granules, including GZMB and GZMH, was dominant in the population with latent infection (IgG+IgM− group)." (PMID 40343282, 2025). "Thus, increased expression of effector molecules like granzyme B may assist TRM to limit the spread of pathogen in immune privileged site like brain and may also help to enhance protection against viral spread following reactivation of latent infection." (PMID 26720146, 2015).
leprosy (4 papers, 2011 to 2025). Leprosy is a chronic infectious disease affecting primarily the skin and peripheral nervous system. "Together, the results indicate that LipoK could contribute to protective host response against leprosy and eventually kill the bacteria, through the production of perforin, granulysin and granzyme B in T cells." (PMID 22132248, 2011). "The mechanisms related to the outcome of reversal reaction in HIV/leprosy patients seem to involve the participation of effector memory CD8+ T cells, together with greater perforin/granzyme B production." (PMID 32849508, 2020).
lymphopenia (4 papers, 2015 to 2024). Reduction in the number of lymphocytes. "Acute infection often involves lymphopenia and a predominance of CD8+ T cells expressing CD69, CD107a, granzyme B, and perforin, targeting virus-infected cells." (PMID 39596565, 2024).
ovarian tumors (4 papers, 2013 to 2021). "In vivo studies demonstrated the prolonged overall survival upon combined treatment of 968 with anti-PD-L1 accompanied by increased granzyme B secretion by CD4+ and CD8+ T cells isolated from ovarian tumor xenografts." (PMID 34944392, 2021).
primary immunodeficiency (4 papers, 2016 to 2025). "The circle plot representation of KEGG results highlighted specific enrichments: CD3E and CD8A were significantly enriched in primary immunodeficiency, while GZMB and PRF1 were notably enriched in allograft rejection." (PMID 39974584, 2025).
Primary Sjögren's Syndrome (4 papers, 2016 to 2023). "Moreover, they demonstrated that GZMB and IL-21 serum levels are highly correlated in SLE and that CD5+ B cells from SLE and Sjögren syndrome patients, which constitutively expressed GZMB, displayed higher expression of IL-21 receptor." (PMID 35359922, 2022).
sarcoma (4 papers, 2013 to 2024). A usually aggressive malignant neoplasm of the soft tissue or bone. "T‐cells in the sarcoma microenvironment exhibited elevated levels of cytotoxicity (GZMB, GNLY and KLRD1), exhaustion (HAVCR2, CD38, CD160, CXCL13 and CX3CR1), and inflammation (IL33, PPARG, IL6R and SOCS3), suggesting an activated but exhausted phenotype." (PMID 39658531, 2024). "In all 3 autologous sarcoma PDX/TIL pairs, coculture of PDX-derived cells with autologous attIL12-TILs dramatically stimulated IFNγ and granzyme B production." (PMID 39574893, 2024).
AIDS (3 papers, 2015 to 2017). A syndrome resulting from the acquired deficiency of cellular immunity caused by the human immunodeficiency virus (HIV). "We additionally observed that gut-associated pDCs in HIV/AIDS cases upregulate the proapoptotic enzyme granzyme B; however, no granzyme B was observed in the pDCs of control biopsies." (PMID 26441989, 2015). "It has also been reported that GZMB-dependent killer pDCs also upregulate the neural adhesion marker CD56; therefore, we additionally probed the same biopsies with anti-CD56 and observed a number of CD303+/CDCD56+ cells in the biopsies of HIV/AIDS cases." (PMID 26441989, 2015).
aortic aneurysm (3 papers, 2012 to 2024). A ruptured aneurysm located in the wall of the proximal portion of the descending aorta proceeding from the arch of the aorta. "Further exploration of SA3N’s effects on GzmB and decorin degradation presents a promising avenue targeting GzmB for therapeutic intervention in aortic aneurysms." (PMID 38846935, 2024).
atopic dermatitis (3 papers, 2012 to 2024). "Granzyme B (GZMB), a serine protease with cytotoxic and immunomodulatory functions, shows elevated levels in blood plasma of patients with atopic dermatitis (AD)." (PMID 37470818, 2023). "In atopic dermatitis (AD), a chronic inflammatory skin disease, characterized by eczematous skin lesions, intense pruritus, epidermal barrier defects, and by a dysregulation of the immune system, an increase of GZMB expression in CD4+ and CD8+ T cells was observed." (PMID 37470818, 2023). "The results indicate a significant decrease in MAIT cells and CD69 subsets in atopic dermatitis, coupled with elevated CD38 and polyfunctional MAIT cells producing TNFα and Granzyme B (TNFα+/GzB+)." (PMID 38542456, 2024).
autoimmune hepatitis (3 papers, 2022 to 2025). Hepatitis caused by autoantibodies. "Granzyme B producing cytotoxic CD103+CD69+CD8+ Trm cells could contribute to liver damage in autoimmune hepatitis (AIH)." (PMID 40607400, 2025). "Therefore, we believe these results collectively indicate that PD‐1+CD8+ T cells can promote caspase‐1 activation and induce pyroptosis in target cells through the production of granzyme B. This provides a new understanding of the pathogenesis of autoimmune liver disease." (PMID 39494472, 2025).